AKT1 (AKT serine/threonine kinase 1)
Diseases named in the same sentence as AKT1 in open-access papers (continued):
Sharing a sentence is not in itself a finding about the gene and the disease.
psychiatric disorder (12 papers, 2008 to 2025). A disorder characterized by behavioral and/or psychological abnormalities, often accompanied by physical symptoms. "AKT1 dysregulation is considered an integral component in the pathogenesis of multiple psychiatric disorders." (PMID 38505421, 2024).
bacterial infection (11 papers, 2011 to 2025). "Macrophage derived AKT1 is strongly phosphorylated during bacterial infections and several AKT1 inhibitors were shown to control intracellular replication of mycobacteria." (PMID 24401837, 2014). "Taken together our findings suggest a central role for Akt1 in the regulation of defensin expression that is responsible for the clearance of bacterial infection and that sNAG treatment activates these pathways in wild type animals." (PMID 21559496, 2011). "sNAG treatment decreases bacterial infection of cutaneous wounds infected with Staphylococcus aureus in wild type control animals but not in similarly treated Akt1 null animals." (PMID 21559496, 2011).
myopathy (8 papers, 2018 to 2024). A disease of the muscle in which the muscle fibers do not function properly. "The authors found that the kinase Akt1 phosphorylates Ser458 and speculated that myopathy-causing LMNA mutations render Ser458 accessible to Akt1 through a conformational change of the Ig fold domain." (PMID 33030403, 2020).
blood cancer (3 papers, 2017 to 2025).
gynecological tumors (3 papers, 2017 to 2026). "Here, we describe the rationale and steps taken to deliver an analytically validated castPCRTM assay to detect the low prevalence AKT1 E17K mutation in FFPE breast and gynecological tumor tissue samples." (PMID 28472036, 2017).
AKT1 also shares sentences with these, for which no sentence is quoted: diffuse large B-cell lymphoma (26 papers); skin cancer (26); kidney diseases (24); small cell lung carcinoma (24); Glucose intolerance (22); hematological malignancies (21); gallbladder cancer (20); metastatic carcinoma (15); medulloblastoma (14); colorectal tumor (13); fibrosis (13); chronic lymphocytic leukemia (12); gastrointestinal tumors (12); laryngeal carcinoma (11); retinoblastoma (11); pancreatic adenocarcinoma (10); T-cell acute lymphoblastic leukemia (10); amyotrophic lateral sclerosis (9); Hepatitis (9); uveal melanoma (9); acute leukemia (8); anaplastic thyroid cancer (8); Burkitt lymphoma (8); chordoma (8); hypertrophy (8); idiopathic pulmonary fibrosis (8); myopia (8); urothelial carcinoma (8); adenomyosis (7); atopic dermatitis (7).
A further 550 diseases each share a sentence with AKT1 in 7 papers or fewer.